ALKBH5 (alkB homolog 5, RNA demethylase)
Description:
Dioxygenase that specifically demethylates N(6)- methyladenosine (m6A) RNA, the most prevalent internal modification of messenger RNA (mRNA) in higher eukaryotes. Demethylates RNA by oxidative demethylation, which requires molecular oxygen, alpha-ketoglutarate and iron. Demethylation of m6A mRNA affects mRNA processing, translation and export. Can also demethylate N(6)-methyladenosine in single-stranded DNA (in vitro). Required for the late meiotic and haploid phases of spermatogenesis by mediating m6A demethylation in spermatocytes and round spermatids: m6A demethylation of target transcripts is required for correct splicing and the production of longer 3'-UTR mRNAs in male germ cells (By similarity). Involved in paraspeckle assembly, a nuclear membraneless organelle, by undergoing liquid-liquid phase separation. Paraspeckle assembly is coupled with m6A demethylation of RNAs, such as NEAT1 non-coding RNA. Also acts as a negative regulator of T-cell development: inhibits gamma-delta T-cell proliferation via demethylation of JAG1 and NOTCH2 transcripts (By similarity). Inhibits regulatory T-cell (Treg) recruitment by mediating demethylation and destabilization of CCL28 mRNAs (By similarity).
Synonyms: ABH5; OFOXD1; FLJ20308; OFOXD
Tractability: Small molecule: a structure with a bound ligand is known; a high-quality ligand is known. PROTAC: UniProt records ubiquitination sites on it; ubiquitination databases record sites on it; its protein half-life has been measured; a small molecule that binds it is known.
Target class: Enzyme; Oxidoreductase
Chemical probes: ALKBH5-IN-1
Gene: Protein-coding gene on chromosome 17 (18,183,078 to 18,209,954, forward strand). Ensembl gene ENSG00000091542.
Subcellular location: Nucleus speckle; Nucleus, nucleoplasm
Subcellular location (Human Protein Atlas): Cytosol; Nucleoplasm; Golgi apparatus
Pathways (Reactome):
DNA Repair: Reversal of alkylation damage by DNA dioxygenases
Gene Ontology:
Molecular function: 2-oxoglutarate-dependent dioxygenase activity; molecular condensate scaffold activity; mRNA N6-methyladenosine dioxygenase activity; RNA binding; oxidative RNA demethylase activity
Biological process: membraneless organelle assembly; mRNA destabilization; regulation of mRNA export from nucleus; regulation of mRNA processing; regulation of translation; response to hypoxia; spermatogenesis; mRNA processing; regulation of mRNA stability
Cellular component: nuclear speck; nucleus; paraspeckles; nucleoplasm
Genetic constraint (gnomAD): Loss-of-function variants: 2 observed, 33.08 expected, observed/expected ratio (o/e) 0.0605, 90% interval 0.024 to 0.19. The synonymous counts are far from expectation, so gnomAD's model fits this gene poorly and the ratio says little. Missense variants: 352 observed, 570.16 expected, observed/expected ratio (o/e) 0.62, 90% interval 0.56 to 0.67. Synonymous variants: 300 observed, 242.14 expected, observed/expected ratio (o/e) 1.24, 90% interval 1.13 to 1.36.
Homologues: Orthologues: chimpanzee ALKBH5 (100% identical), macaque ALKBH5 (100% identical), dog ALKBH5 (99% identical), guinea pig ALKBH5 (98% identical), rabbit ALKBH5 (98% identical), rat Alkbh5 (98% identical), mouse Alkbh5 (97% identical), pig ALKBH5 (96% identical), tropical clawed frog alkbh5 (69% identical), zebrafish alkbh5 (65% identical).
Diseases named in the same sentence as ALKBH5 in open-access papers:
ALKBH5 is named in the same sentence as 249 diseases in open-access papers, as found by Europe PMC text mining. Sharing a sentence is not in itself a finding about the gene and the disease. The quoted sentences say what the papers report.
glioblastoma (158 papers, 2017 to 2025). The most malignant astrocytic tumor (WHO grade IV). "Abnormal ALKBH5 expression has been implicated in the pathogenesis of various cancers, including glioblastoma." (PMID 38785979, 2024). "ALKBH5 promoted cancer stem cell self‐renewal in acute myeloid leukaemia, and caused glioblastoma tumourigenesis by sustaining FOXM1 expression." (PMID 36864711, 2023). "ALKBH5 is a m6A demethylase that is associated with the development and progression of multiple cancer types, such as glioblastoma, ovarian cancer, lung cancer, liver cancer, pancreatic cancer and osteosarcoma." (PMID 35444654, 2022). "ALKBH5, induced by hypoxia in glioblastoma multiforme (GBM), is responsible for tumor-associated macrophage (TAM) recruitment, leading to a suppressive TIME by facilitating CCX8/IL-8 secretion." (PMID 35720276, 2022). "The low expression of m6A regulators METTL14 in HCC and the overexpression of the m6A regulator ALKBH5 in glioblastoma have been both associated with poor prognosis." (PMID 33643384, 2021). "In glioblastoma, highly expressed ALKBH5, also functioning as an m6A eraser, was associated with a poor prognosis in glioblastoma patients." (PMID 32346127, 2020). "Dataset analysis provided evidence that the expression of m6A demethylase ALKBH5 in glioblastoma cells is associated with poor prognosis." (PMID 30279357, 2018). "In addition, it has been found that high ALKBH5 expression in glioblastoma stem cells is associated with poor clinical outcome in glioblastoma patients." (PMID 40356909, 2025). "Upregulation of ALKBH5 is associated with poor prognosis for the patients with glioblastoma." (PMID 31804607, 2020). "Moreover, the protein eraser ALKBH5 seems to display a high expression in glioblastoma and sustains tumor cells growth via fork head box M1, thus ALKBH5 deregulation is linked to a poor outcome." (PMID 30654440, 2019). "Silencing ALKBH5 in glioblastoma multiforme (GBM) notably suppresses hypoxia-induced tumor-associated macrophage (TAM) recruitment and immunosuppression in allograft tumors by regulating CXCL8/IL-8 secretion." (PMID 36225914, 2022). "Several studies showed that FTO and ALKBH5 (erasers) expression were associated with a less favorable prognosis in patients with glioblastoma (GBM)." (PMID 36281789, 2022). "For instance, while ALKBH5 exhibits tumor‐suppressive activity in pancreatic cancer, it plays a tumor‐promoting role in glioblastoma." (PMID 40448344, 2025). "Imidazobenzoxazin-5-thione MV1035, a new sodium channel blocker, demonstrates significant inhibition of migration and invasion in U87 glioblastoma cell lines by reducing ALKBH5 expression." (PMID 40958857, 2025). "For example, in glioblastoma, ALKBH5 maintains tumorigenicity of cancer stem-like cells by inducing the expression of FOXM1." (PMID 40603319, 2025). "Studies demonstrate that elevated expression of ALKBH5 enhances glioblastoma (GBM) radioresistance by modulating homologous recombination (HR)." (PMID 40823093, 2025). "ALKBH5 accelerates tumor growth in glioblastoma (GBM) by enhancing FOXM1 expression through the removal of m6A." (PMID 41446042, 2025). "The expression of ALKBH5 is positively correlated with glioma malignant phenotypes, suggesting its potential as a promising prognostic factor for glioblastoma patients." (PMID 40097417, 2025). "Downregulation of ALKBH5 in glioblastoma cells inhibits the expression of vascular endothelial growth factor A (VEGFA) and impairs the angiogenic potential of co-cultured HUVECs." (PMID 40097417, 2025). "For example, Ena15 is considered a non-competitive inhibitor of ALKBH5, while Ena21 is a competitive inhibitor of ALKBH5; both have been demonstrated to suppress the progression of glioblastoma." (PMID 40001461, 2025). "As a possible ALKBH5 deubiquitination enzyme, Ub‐specific peptidase 36 (USP36) is essential for ALKBH5 stability and AlkBH5‐mediated gene expression regulation in glioblastoma (GBM)." (PMID 40919129, 2025).
glioblastoma (continued). "EGFR signaling can also suppress m6A levels in glioblastoma by inhibiting ALKBH5 nuclear export, thereby enhancing the function of the m6A eraser." (PMID 38398118, 2024). "Conversely, when USP36 was removed, there was a decrease in ALKBH5 expression, which resulted in the inhibition of tumor growth in glioblastoma xenograft models." (PMID 38785979, 2024). "More recently, USP36 facilitates the development of glioblastoma through mediating ALKBH5 protein stability." (PMID 38517383, 2024). "ALKBH5 is an N6-methyladenosine demethylase that results in increased oncogene expression responsible for glioblastoma proliferation." (PMID 38928445, 2024). "Inhibition of ALKBH5 with Ena21 and Ena15 successfully inhibits cell proliferation of glioblastoma multiforme‐derived cells and decreases cell population in the synthesis phase of the cell cycle." (PMID 38545841, 2024). "ALKBH5 decreased the expression of PD-L1 in glioblastoma (GB) by regulating the stability of ZDHHC3 mRNA." (PMID 39220683, 2024). "Downregulation of ALKBH5 in glioblastoma cells results in a significant decrease in CXCL8/IL8 production, leading to diminished recruitment of hypoxia-induced TAMs and attenuated immunosuppression." (PMID 38398118, 2024). "ALKBH5 overexpression in glioblastoma stem cells contributes to increased resistance to radiation and enhanced invasive capabilities, and its activity is regulated by EGFR signaling, impacting ferroptosis through m6A modulation." (PMID 38474421, 2024). "Subsequent validation experiments confirmed that knockdown of ALKBH5 significantly impacted the angiogenesis promotion ability of glioblastoma (GBM) both in vitro and in vivo." (PMID 38221546, 2024). "For instance, EGFR signaling suppresses m6A modification in glioblastoma by phosphorylating ALKBH5 via Src kinase, which prevents ALKBH5's CRM1‐mediated nuclear export, enhancing m6A demethylation in the nucleus." (PMID 39377984, 2024). "On the other hand, acquired hypermethylation of mismatch repair genes MSH6, LTBP4, and ALKBH5 are almost exclusively observed in recurrent glioblastoma post-initial treatment." (PMID 38928445, 2024). "ALKBH5 knockdown on glioblastoma-derived stem-like cells (GSCs) was shown to reduce their proliferation." (PMID 38398118, 2024). "In glioblastoma stem-like cells (GSCs), high expression of ALKBH5 is closely related to malignant characteristics." (PMID 39192357, 2024). "ALKBH5 mediates Temozolomide resistance in glioblastoma by demethylating the SOX2 transcript, increasing its expression." (PMID 38545841, 2024). "The regulation of ALKBH5 by USP36 underscores its role in glioblastoma progression and sensitivity to TMZ." (PMID 38474421, 2024). "The role of m6A in cancer stem cells was first evidenced when ALKBH5 was found predominately in the niches of cancer stem cells in human glioblastoma tissues." (PMID 38398118, 2024). "A study has demonstrated the role of ALKBH5 in promoting radio-resistance in GBM through mediating homologous repair mechanisms in patient-derived glioblastoma cell culture." (PMID 37444417, 2023). "In glioblastoma, ALKBH5 promotes tumor growth by lowering the m6A methylation in target mRNA transcripts and increasing the FOXM1 expression." (PMID 37325047, 2023). "A more recent study has corroborated the efficacy of such an approach, demonstrating two novel inhibitors of ALKBH5, Ena15 and Ena21, that inhibited cell proliferation of glioblastoma cell lines." (PMID 37444417, 2023). "ALKBH5 is upregulated in cancers and plays oncogenic roles as an m6A demethylase in glioblastoma, acute myeloid leukemia, gastric cancer, breast cancer, and ovarian cancer." (PMID 37369679, 2023). "AlkB homolog 5, RNA demethylase (ALKBH5) is abnormally highly expressed in glioblastoma multiforme (GBM) and is negatively correlated with overall survival in GBM patients." (PMID 37325047, 2023).
glioblastoma (continued). "As an oncogene, ALKBH5 is upregulated in a variety of cancer tissues compared to non-cancerous tissues, including breast cancer (BC), glioma and glioblastoma, lung cancer, ovarian cancer, acute myeloid leukemia (AML), GC, and colon cancer." (PMID 37007161, 2023). "Dynamic m6A modification is a putative mechanism in this process, and a study in GBM cells has shown the hypoxia-induced upregulation of ALKBH5 in a dependant manner in glioblastoma-derived cell culture." (PMID 37444417, 2023). "There is also evidence of a role for Alkbh5 in tumor development; Alkbh5 regulates the self-renewal and proliferation capacity of tumor stem cells of several cancers, including glioblastoma, breast cancer, and leukemia." (PMID 37588656, 2023). "ALKBH5 functions as an oncogene in many cancers, including glioblastoma, breast cancer and esophageal squamous cell cancer." (PMID 35979628, 2022). "ALKBH5 is a promising target for surmounting radioresistance and reducing recurrence of glioblastoma." (PMID 35843942, 2022). "Wu’s team reported that ALKBH5, along with the hypoxic gene, was induced in glioblastoma models under hypoxic conditions." (PMID 35625706, 2022). "RNA demethylase ALKBH5 is highly expressed in glioblastoma stem cells (GSCs) and promotes tumorigenicity through the binding mRNA of the FOXM1 transcription factor by interacting with lncRNA FOXM1-AS." (PMID 36012529, 2022). "One of the main erasers of m6A, ALKBH5, which is upregulated in glioblastoma cells, demethylated glucose-6-phosphate dehydrogenase (G6PD) mRNA, promoting the translation and activation of the pentose phosphate pathway (PPP)." (PMID 36012529, 2022). "Suppression of ALKBH5 in glioblastoma cells significantly decreased CXCL8/IL8 production, diminished hypoxia-induced TAM recruitment, and immunosuppression in intracranial transplanted tumors." (PMID 35625706, 2022). "And ALKBH5 was highly expressed in glioblastoma stem-like cells (GSCs) and maintained tumorigenic activity of GSCs via maintaining FOXM1 expression and cell proliferation program." (PMID 35444654, 2022). "The expression of ALKBH5 is correlated with poor prognosis in glioblastoma and promotes the proliferation and tumor progression of glioblastoma stem cells by enhancing FOXM1 expression." (PMID 36360287, 2022). "MV1035 was tested following its in silico predicted ability to act as an inhibitor against ALKBH2 and ALKBH5, both involved in maintaining the tumorigenicity of glioblastoma." (PMID 35053068, 2022). "For instance, ALKBH5 has been shown to maintain the tumorigenicity of glioblastoma stem-like cells by sustaining FOXM1 expression and cell proliferation program." (PMID 35031597, 2022). "ALKBH5, an important participant in m6A methylation modification, has also been reported in other tumors, such as leukemia, glioblastoma, pancreatic cancer, lung cancer and breast cancer." (PMID 35114989, 2022). "Recently, the m6A demethylase ALKBH5 was discovered to facilitate invasion and radioresistance of glioblastoma stem cells by downregulating the expression of HRR-related genes including CHK1 and RAD51." (PMID 35843942, 2022). "In glioblastoma, elevated ALKBH5 enhanced cell self-renewal, proliferation, and tumorigenicity by the demethylation of m6A." (PMID 36293529, 2022). "As early as 2017, Huang’s group uncovered a critical function for ALKBH5 and provided insight into the important roles of m6A methylation in glioblastoma." (PMID 35625706, 2022). "Only in glioblastoma stem-like cells (GSCs) and leukemia stem cells which have relative unequivocal marker, ALKBH5 was proved to be highly expressed in purified cancer stem cells." (PMID 35414790, 2022). "ALKBH5 also plays an oncogenic or tumor suppressive role in different kinds of cancers, such as breast cancer, glioblastoma, ovarian cancer, lung cancer, liver cancer, pancreatic cancer, gastrointestinal cancer, acute myeloid leukemia (AML) and osteosarcoma." (PMID 35444654, 2022).
glioblastoma (continued). "Concretely, ALKBH5 acts as an oncogene in glioblastoma, acute myeloid leukemia, breast cancer, and ovarian carcinoma, while functioning as a tumor suppressor in lung cancer, hepatocellular carcinoma, and osteosarcoma." (PMID 34733841, 2021). "Most recently, ALKBH5 was found to have oncogenic roles in glioblastoma and breast cancer cells, suggesting it contributes to mRNA m6A methylation in cancer." (PMID 34016959, 2021). "It has been reported that ALKBH5 is overexpressed in various cancers, including breast cancer, glioblastoma, ovarian cancer, and gastric cancer." (PMID 34055982, 2021). "ALKBH5-induced overexpression of FOXM1 contributes to the tumorigenicity of glioblastoma stem-like cells." (PMID 34491904, 2021). "ALKBH5 regulates FOXM1 expression by demethylating the nascent transcripts of FOXM1 in glioblastoma stem-like cells." (PMID 33428593, 2021). "ALKBH5 has been shown to be responsible for tumor proliferation in different cancers, including breast cancer, glioblastoma and LADC, so its inhibition can yield good clinical outcomes if implemented." (PMID 34526985, 2021). "LncRNA SOX2OT elevates SOX2 expression through ALKBH5-mediated epigenetic regulation of glioblastoma and promotes temozolomide resistance." (PMID 34178697, 2021). "In glioblastoma, ALKBH5 interacts with the lncRNA FOXM1-AS, which enhances the demethylation of the 3′ UTRs of FOXM1 transcripts to promote tumor proliferation and tumorigenesis." (PMID 35047491, 2021). "ALKBH5 is involved in the progression of multiple cancers, playing an oncogenic role in glioblastoma while suppressing the tumour proliferation and development in pancreatic cancer and NSCLC." (PMID 34802443, 2021). "In vitro and in vivo experiments showed that the knockout of FOXM1-AS and ALKBH5 affected the tumorigenicity of GSCs related to FOXM1, revealing the importance of demethylase ALKBH5 and m6A in glioblastoma." (PMID 32948220, 2020). "In agreement with the enrichment of ALKBH5 expression in GSCs, the protein colocalized, in tumour tissues, with two typical stemness markers for glioblastoma, SOX2 and Nestin." (PMID 32316617, 2020). "Zhang et al40 found that expression of ALKBH5 was upregulated in glioblastoma stem‐like cells (GSCs)." (PMID 32091154, 2020). "ALKBH5 also maintains tumorigenicity of glioblastoma stem-like cells by sustaining FOXM1 expression and cell proliferation program." (PMID 33489865, 2020). "ALKBH5 was also highly expressed in glioblastoma stem-like cells (GSCs) and the knockdown of ALKBH5 attenuated the growth of patient-derived GSCs." (PMID 32101138, 2020). "ALKBH5, another important eraser of m6A methylation, has oncogenic roles in breast cancer and glioblastoma, while it inhibits cancer cell migration and invasion in pancreatic cancer." (PMID 32709063, 2020). "Forkhead Box protein M1 (FOXM1) abundance was increased when ALKBH5 was upregulated in glioblastoma." (PMID 31931709, 2020). "ALKBH5 expression was also elevated in glioblastoma stem-like cells (GSCs), demethylated FOXM1 nascent transcripts and enhanced the expression of FOXM1, thus enhancing stem cells self-renewal, proliferation and tumorigenesis." (PMID 32742194, 2020). "Forkhead box M1 (FOXM1), which is vital for glioblastoma stem cell proliferation and tumorigenesis, is significantly upregulated by ALKBH5 via its demethylation activity on m6A." (PMID 32709063, 2020). "And the imidazobenzoxazin-5-thione MV1035 inhibited glioblastoma cell line migration and invasion via inhibiting ALKBH5." (PMID 32742194, 2020). "The eraser ALKBH5 was observed to be up regulated in glioblastoma stem-like cell (GSCs), leading to the initiation and development of glioblastoma." (PMID 32038982, 2020). "ALKBH5 has been found upregulated in glioblastoma and prompts the proliferation of glioblastoma stem-like cells (GSCs)." (PMID 32767982, 2020).